IKZF1 (IKAROS family zinc finger 1)
Diseases named in the same sentence as IKZF1 in open-access papers (continued):
Sharing a sentence is not in itself a finding about the gene and the disease.
acute lymphoblastic leukemia (continued). "It is possible that BCR-ABL-positive acute lymphoblast leukemia cells with IKZF1 deletion are more vulnerable to DNA damage agents such as PARPi." (PMID 35414773, 2022). "Ikaros (IKZF1) is a DNA-binding protein that functions as a master regulator of hematopoiesis and the immune system, as well as a tumor suppressor in acute lymphoblastic leukemia (ALL)." (PMID 32085659, 2020). "Cordon-Bleu WH2 Repeat Protein (COBL) has been reported to play an important role in the reorganization of the actin cytoskeleton, and as a hotspot for IKZF1 deletions in acute lymphoblastic leukemia." (PMID 33614471, 2020). "IKZF1 alterations are recurrent in acute lymphoblastic leukaemia (ALL) and chronic myeloid leukaemia that progress into lymphoid blast crisis." (PMID 29743561, 2018). "Furthermore, genetic alteration of Ikaros family zinc finger protein 1 (IKZF1) in acute lymphoblastic leukemia (ALL) is associated with poor outcome and high relapse after chemotherapy." (PMID 24600454, 2014). "Deletions of IKAROS (IKZF1) frequently occur in B-cell precursor acute lymphoblastic leukemia (B-ALL) but the mechanisms by which they influence pathogenesis are unclear." (PMID 22848414, 2012). "A recently characterized high-risk subgroup in acute lymphoblastic leukemia (ALL) is defined by the IKZF1plus profile, which is marked by the co-occurrence of IKZF1 deletions alongside deletions in CDKN2A/B, PAX5, or the PAR1 region, in the absence of ERG gene alterations." (PMID 41228238, 2025). "IKZF1 functions as a tumor suppressor in acute lymphoblastic leukemia." (PMID 40428397, 2025). "Using retroviral transduction of Ikzf1 deletion exon 4 to 7 (IK6) in pre-B acute lymphoblastic leukemia cell line (JM1), we developed a cell line model that recapitulated the phenotype of increased adhesion and stemness as observed in B-ALL mouse models and patient samples." (PMID 39029626, 2024). "IKZF1 is an important regulator in B-cell precursor acute lymphoblastic leukemia." (PMID 34996354, 2022). "Human chromodomain helicase DNA binding protein 5 (CHD5), Krüppel-like factor 2 (KLF), Retinoblastoma protein-interacting zinc finger 1 (RIZ), and IKAROS family zinc finger 1 (IKZF1) are among the genes that regulates gene transcription, and are inactivated in acute lymphoid leukemia (ALL)." (PMID 28580304, 2017). "IKZF1 alterations are relatively common (30–50%) in adult acute lymphoblastic leukemia (ALL) patients, and the most common pattern of alteration is heterozygous deletion of either the whole gene or specific exons with subsequent loss of function." (PMID 40805192, 2025). "IKZF1 deletions have also been observed in acute lymphoblastic leukemia/lymphoblastic lymphoma (ALL/LBL)." (PMID 39272737, 2024). "Germline or somatic mutations of IKZF1 demonstrate quite variable clinical phenotypes, ranging from primary immunodeficiency (PID)/inborn errors of immunity (IEI) to autoimmune diseases and to even hematological malignancies such as acute lymphoblastic leukemia." (PMID 38978740, 2024). "Genetic lesions of IKZF1 are recurrent events in B-cell acute lymphoblastic leukemia (ALL) conferring poor prognosis." (PMID 37833543, 2023). "An example of low penetrance common genetic variations associated with cancer risk includes IKZF1 and ARID5B genes in pediatric acute lymphoblastic leukemia (ALL)." (PMID 34155975, 2021). "Genetic data has revealed that the loss of IKZF1 and IKZF3 results in a block of lymphoid lineage differentiation and a susceptibility to develop acute lymphoblastic leukemia (ALL)." (PMID 30760870, 2019).
acute lymphoblastic leukemia (continued). "Interaction between the SNP rs4132601 (IKZF1) and maternal use of home insecticides during pregnancy, preconception paternal smoking, breastfeeding, repeated early common infections and birth order, in their relation with childhood acute lymphoblastic leukemia." (PMID 25806972, 2015). "Clinical studies found that genetic alterations in Ikaros genes correlates to a poor outcome in high-risk acute lymphoblastic leukemia (ALL) patients and it was highlighted that the 83.7% of patients with Philadelphia chromosome-carrying ALL had partially or total decrease of IKZF1 gene expression." (PMID 38694501, 2024). "By conducting genome-wide association studies (GWASs), we and other independent groups identified multiple top inherited predispositions to acute lymphoblastic leukemia (ALL) susceptibility, including single nucleotide polymorphisms (SNPs) at ARID5B, IKZF1, GATA3 and etc.." (PMID 33193587, 2020). "In acute lymphoblastic leukemia, COBL is a hotspot for IKZF1 deletions, and we will study the function of COBL in HNSCC in the future." (PMID 33614471, 2020). "For the human-centric brain network comparisons, u(HB, MB), the genes IKZF1 and HNF1B, which are related to acute lymphoblastic leukemia and diabetes mellitus type 2 respectively, were found among the centralmost genes." (PMID 29161290, 2017). "Since 1999, IKZF1 has been implicated in the roles, involved in several hematologic traits or abnormalities, such as erythrocyte measures, SLE, and acute lymphoblastic leukemia (ALL)." (PMID 28552951, 2017). "Associations between childhood acute lymphoblastic leukemia (ALL) and rs4132601 (IKZF1) polymorphisms by non-genetic factors: allelic OR in the whole sample and by ALL major subtypes, in the ESCALE study, France 2003–2004." (PMID 25806972, 2015). "Common allelic variants in IKZF1 (7p12.2), ARID5B (10q21.2), and CEBPE (14q11.2), which are directly related to hematopoietic differentiation and development, have been repeatedly and significantly associated with childhood acute lymphoblastic leukemia (ALL)." (PMID 24564228, 2014). "IKZF1 deletions are common in de novo acute lymphoblastic leukemia (ALL), but have not been described in de novo AML." (PMID 32640569, 2020). "IKZF1 deletions are an unfavorable prognostic factor in children with Philadelphia chromosome positive (Ph+) as well as negative (Ph−) acute lymphoblastic leukemia (ALL)." (PMID 26269779, 2015). "Association between childhood acute lymphoblastic leukemia (ALL), rs10740055 (ARID5B), rs4132601 (IKZF1), and the non-genetic factors of interest, in the ESCALE study, France 2003–2004." (PMID 25806972, 2015). "Optical Genome Mapping (OGM) enables high-resolution detection of structural genomic alterations with established prognostic significance in acute lymphoblastic leukemia (ALL), including deletions affecting CDKN2A/B, IKZF1, and PAX5 loci." (PMID 41228238, 2025). "Notably, Late-Pro patients showed good prognosis despite frequent single-copy losses or mutations in IKZF1 (n = 14/22, 64%), suggesting single-copy alterations in IKZF1 are not responsible for the high-risk nature of BCR-ABL1 lymphoblastic leukemia." (PMID 37337105, 2023). "Additionally, we identified a single individual with B-cell precursor acute lymphoid leukemia with two intragenic deletions involving IKZF1 and PAX5, in the absence of an ERG deletion, suggestive of the IKZF1plus phenotype." (PMID 37686670, 2023). "The SNPs (IKZF1 rs11978267, ARID5B rs10821936 and rs10994982, CEBPE rs2239633) were genotyped in 265 cases [169 acute lymphoblastic leukemia (ALL) and 96 acute myeloid leukaemia (AML)] and 505 controls by Taqman allelic discrimination assay." (PMID 24564228, 2014). "Unlike the B cell acute lymphoblastic leukemia (ALL), where more than 30% of cases have IKZF1 genetic alterations, less than 10% of patients in AML have IKZF1 genetic mutations." (PMID 33807974, 2021).
acute lymphoblastic leukemia (continued). "Genome‐wide studies demonstrated that 60% of all B‐cell precursor acute lymphoblastic leukemia (B‐ALL) cases carry genetic alterations in genes coding for regulators of B cell development, with the most commonly affected transcription factor genes being PAX5, EBF1, and IKZF1 (Ikaros)." (PMID 35156727, 2022).
multiple myeloma (81 papers, 2014 to 2025). "As a result, lenalidomide causes ubiquitination and selective degradation of IKZF1/3, which are necessary for the survival of myeloma cells, which explains its clinical efficacy." (PMID 40650173, 2025). "UBE2G1-deficient myeloma cells, however, remained sensitive to a more potent IKZF1/3 degrader CC-220." (PMID 30234487, 2018). "They analyzed myeloma cell lines and demonstrated that loss of IKZF1 and IKZF3 is necessary and sufficient for Len’s therapeutic effect." (PMID 29454372, 2018). "We also detected additive loss of IKAROS/IKZF1 and the myeloma pro‐survival factors IRF4 and FOXM1." (PMID 31714026, 2020). "The key mechanism of immunomodulators used in myeloma therapy is to promote the ubiquitination of transcription factors IKAROS Family Zinc Finger 1 (IKZF1) and IKAROS Family Zinc Finger 3 (IKZF3) through the action of cereblon, an E3 ligase." (PMID 40259951, 2025). "IMiDs bind to CRBN and redirect its E3 ubiquitin ligase activity to degrade key transcription factors (e.g., IKZF1/3), leading to myeloma cell death." (PMID 40650115, 2025). "In human myeloma cells, Ikaros zinc finger 1 (IKZF1) was identified as the pivotal transcriptional activator of SLAMF7; however, the murine SLAMF7 (mSLAMF7) promoter was found to be regulated by YY1 in B cells." (PMID 40247106, 2025). "The compound CC-220 is currently in phase III clinical trials for the treatment of systemic lupus erythematosus and relapsed/refractory multiple myeloma, through the induction of IKZF1 and IKZF3 protein degradation." (PMID 40730655, 2025). "CFT7455, a IKZF1/3 degrader developed by C4 Therapeutics, is in Phase 1 trials for relapsed/refractory multiple myeloma (RRMM)." (PMID 40574056, 2025). "IMiDs are known to induce degradation of zinc-finger transcription factors in myeloma cells, like IKZF1 and IKZF3, and like SALL4 in embryonic stem cells, which is behind their therapeutic, but also teratogenic functions." (PMID 39972349, 2025). "Early-phase trials explored the potential of targeting proteins like IKZF1/3 in multiple myeloma and IRAK4 in autoimmune diseases." (PMID 40574056, 2025). "For example, lenalidomide, pomalidomide, and thalidomide analogs, by binding to Cereblon, induce selective destruction of IKZF1/3 transcription factors in myeloma cells." (PMID 40650173, 2025). "These compounds serve as molecular glues, redirecting the CRBN E3 ubiquitin ligase to degrade myeloma-dependency factors, IKZF1 and IKZF3." (PMID 38165043, 2024). "For example, since none of the cell lines in our panel are sensitive to IKZF1 degradation we would miss discovering IKZF1 degraders, which are a component of the front-line therapies for multiple myeloma." (PMID 38228616, 2024). "For instance, lenalidomide causes selective ubiquitination and degradation of IKZF1 and IKZF3 conferring cytotoxicity in multiple myeloma cells." (PMID 37833543, 2023). "In myeloma cells, interferon regulatory factor 4 (IRF4), a transcription factor for myeloma cell growth, is suppressed via the degradation of Ikaros family zinc finger 1/3 (IKZF1/3), inducing a direct anti-myeloma effect." (PMID 38004369, 2023). "IKZF1, a driver gene in multiple myeloma and other B-cell lymphomas, is the molecular target of IMiDs (immunomodulatory drugs) including lenalidomide and pomalidomide, which facilitate CRBN-mediated degradation of the Ikaros family proteins." (PMID 36991428, 2023). "Collectively, our data suggest that c‐FOS is an integral component of the IKZF1 complex in MM cells and primarily mediates activator functions of the complex via direct binding to IKZF1 on the myeloma genome." (PMID 37581569, 2023). "Degradation of IKZF1 and IKZF3 causesinhibition of the proliferation of multiple myeloma cells and suppressionof the differentiation of B-cells." (PMID 35856839, 2023).
multiple myeloma (continued). "CC-92480 induces rapid degradation of the transcription factors IKZF1/3, leading to immune-stimulatory effects and apoptosis of myeloma cells, including those resistant to lenalidomide and pomalidomide." (PMID 36499765, 2022). "In multiple myeloma cells, pomalidomide and lenalidomide induce the breakdown of Ikaros (IKZF1) and Aiolos (IKZF3), resulting in IRF4 downregulation and cell growth defects." (PMID 34764413, 2021). "Inducing the degradation of TFs like a IKZF1 (IKAROS Family Zinc Finger 1) by lenalidomide has led to its approval in the treatment of myeloma." (PMID 33613844, 2021). "As an alternative approach, we employed the thalidomide derivative lenalidomide, which has been shown to induce the proteasomal degradation of IKZF3 (and IKZF1) and is used therapeutically in treating multiple myeloma." (PMID 32321757, 2020). "In Multiple myeloma, the continuous expression of Ikaros family zinc finger protein 1 (IKZF1) and Ikaros family zinc finger protein 3 (IKZF3) is essential for the proliferation and survival of the myeloma cells." (PMID 32591583, 2020). "IMiDs induce the recruitment of specific substrates including IKZF1/3 to E3 ubiquitin ligase and display anti-myeloma effects through the ubiquitination and subsequent proteasomal degradation of IKZF1/3." (PMID 30987296, 2019). "It will also be important to more completely understand how IKZF1 regulates the IgL enhancer in myeloma and in the context of translocation and IMiD-mediated degradation." (PMID 31015454, 2019). "Patients with IgL-translocations fail to benefit from IMiDs, which target IKZF1, a transcription factor that binds the IgL enhancer at some of the highest levels in the myeloma epigenome." (PMID 31015454, 2019). "This phenomenon is notable as IMiDs, which are commonly used as a front-line treatment for myeloma, target IKZF1 for CRBN-mediated ubiquitination and proteasomal degradation." (PMID 31015454, 2019). "IKZF1 is also known to be a key target of thalidomide and its derivatives, used to treat myeloma and 5q-myelodysplasia." (PMID 29588478, 2018). "For example, UBE2G1 inactivation significantly attenuated the degradation of myeloma survival factors IKZF1 and IKZF3 induced by lenalidomide and pomalidomide, hence conferring drug resistance." (PMID 30234487, 2018). "The aim of this study is to assess nucleoprotein expression of IKZF1/3 in patients with relapsed/refractory multiple myeloma (MM) who received lenalidomide-based therapy and correlated them with their clinical outcomes." (PMID 27881177, 2016). "Additionally, overexpression of IKZF1/3 is observed in multiple myeloma (MM), which stimulate malignant proliferation of plasma cells." (PMID 39759140, 2024). "Left panel: In multiple myeloma (MM), IKZF1/3 binds to the canonical IKZF‐binding motif CTTCC in a complex with c‐FOS/c‐JUN to activate the transcription of genes involved in the growth and survival of MM cells such as interferon regulatory factor 4 (IRF4) and SLAMF7." (PMID 37581569, 2023). "Furthermore, genetic susceptibility was indicated in ALL and multiple myeloma, with constitutional mutations in genes such as IKZF1, SH2B3, PAX5 (ALL) and KDM1A/LSD1 (multiple myeloma)." (PMID 36998465, 2023). "Thalidomide and its analogs lenalidomide and pomalidomide directly bind to the cereblon (CRBN) and subsequently recruit neo-substrates IKZF1/3 to the CRL4CRBN E3 ligase, thereby inducing ubiquitination and degradation of IKZF1/3 and exhibiting an anti-myeloma effect." (PMID 35321428, 2022). "Finally, I discuss future perspectives on caspase-8-based therapy for myeloma.via cereblon IKZF1/3 cascade." (PMID 35321428, 2022). "Also, the pan-PIM kinase inhibitor SGI1776 enhances lenalidomide’s anti-myeloma activity due to more effective degradation of IKZF1 and IKZF3 in MM cell lines as well as xenografts of myeloma tumors." (PMID 32987735, 2020).
multiple myeloma (continued). "The loss of pDCs may therefore promote the development of autoimmunity in IKZF1 haploinsufficiency and confer therapeutic benefit in the treatment of multiple myeloma." (PMID 29588478, 2018). "Interestingly, in multiple myeloma cells treatment with lenalidomide increased ubiquitination and subsequent degradation of IKZF1 and IKZF3, demonstrating that small molecules can modulate the CUL4-DDB1-DCAF complex." (PMID 26613412, 2015). "Furthermore, CelMoDs, a class of IKZF1/3 degraders developed by Bristol-Myers Squibb (such as CC-92480, CC-220, and CC-99282), have entered clinical studies for the treatment of relapsed or refractory multiple myeloma (RRMM)." (PMID 40469310, 2025). "To identify unknown components of the IKZF1 complex, we analyzed the genome‐wide binding of IKZF1 in MM cells using chromatin immunoprecipitation‐sequencing (ChIP‐seq) and screened for the co‐occupancy of IKZF1 with other DNA‐binding factors on the myeloma genome using the ChIP‐Atlas platform." (PMID 37581569, 2023). "Additionally, IMiDs have been found not only to have immunomodulative effects on T cells (hence the name), but also to have antiproliferative effects on multiple myeloma cell types by recruiting the transcription factors Ikaros (IKZF1) and Aiolos (IKZF3) for its degradation." (PMID 34577077, 2021). "Hence, we reasoned that resistance to IMiD drugs in myeloma could be ascribed to reduced degradation of IKZF1 and IKZF3 as a result of inactivation of other essential components of the CRL4CRBN ligase complex, for instance the E2 ubiquitin conjugation enzyme." (PMID 30234487, 2018). "Furthermore, three TFs highly expressed in multiple myeloma and pivotal regulators of malignancy-specific gene expression, the Ikaros family zinc finger protein-1 and -3 (IKZF1 and IKZF3) and IRF4, are potent repressors of MICA expression in this hematological cancer." (PMID 29662484, 2018). "In contrast, in the same study, pomalidomide significantly decreased CS1 via targeting IKZF1, a pivotal transcriptional activator of SLAMF7 in myeloma cells." (PMID 40247106, 2025). "These drugs, used in multiple myeloma, bind to CRBN ligase and redirect it against certain B-lymphocyte transcription factors IKZF1 (Ikaros) and IKZF3 (Aiolos)." (PMID 40650173, 2025). "Lenalidomide (Len), another immunomodulator with stronger inhibition of IKZF1 and IKZF3 gene expression, is widely used in the treatment of multiple myeloma." (PMID 39759140, 2024). "Lenalidomide itself is an analogue of thalidomide, and like thalidomide is known to degrade IKZF1 and IKZF3 in multiple myeloma cells." (PMID 39029626, 2024). "The mechanism of action of lenalidomide includes degradation of the transcription factors Ikaros (IKZF1) and Aiolos (IKZF3), which act as central transcription factors regulating various genes involved in the survival of myeloma cells." (PMID 36094683, 2023). "Two zinc finger transcription factors, Ikaros (IKZF1) and Aiolos (IKZF3), which are essential for myeloma cell survival, are recruited to the complex as neo-substrates, resulting in their ubiquitination and subsequent proteasomal degradation." (PMID 36768967, 2023). "Essential transcription factors IKAROS family zinc finger 1 (IKZF1) and IKZF3 in multiple myeloma are targets of CRL4-CRBN E3 ligase." (PMID 37799379, 2023). "Whole‐chromosome images generated by Strand NGS software revealed a significant overlap of the peaks representing IKZF1 and c‐FOS binding to the myeloma genome." (PMID 37581569, 2023). "Co‐occupancy of IKZF1 and c‐FOS on the same consensus in ∼50% of target genes strongly suggests that the two factors form a complex on the myeloma genome." (PMID 37581569, 2023). "Lenalidomide recruits the neo-substrate IKZF1/3 onto CRBN and promotes ubiquitination and subsequent degradation by the CRL4CRBN E3 ligase, thereby exhibiting an anti-myeloma effect." (PMID 35321428, 2022).